INS (insulin)
Diseases named in the same sentence as INS in open-access papers (continued):
Sharing a sentence is not in itself a finding about the gene and the disease.
type 2 diabetes (continued). "Studies have shown enhanced 5αR activity to be associated with obesity and type 2 diabetes, with weight loss resulting in reduced 5αR activity and improvement in insulin sensitivity." (PMID 37339332, 2023). "Coffee consumption has previously been linked to reduced risk of type 2 diabetes and improved glucose metabolism as it reduces the area under the glucose curve and increases the insulin response." (PMID 36978934, 2023). "In clinical studies, plasma leptin levels have been shown to be associated with insulin sensitivity in both healthy and obese women, as well as patients with type 2 diabetes." (PMID 38027100, 2023). "Type 2 diabetes mellitus (T2DM) is a metabolic disease characterized by hyperglycemia caused by insulin resistance or insufficient insulin secretion." (PMID 37599328, 2023). "Well-established risk factors for type 2 diabetes and obesity are a sedentary lifestyle, poor nutrition, insulin resistance, environmental factors and genetics." (PMID 37240215, 2023). "Insufficient insulin secretion is a hallmark of type 2 diabetes and has been attributed to beta cell identity loss characterized by decreased expression of several key beta cell genes." (PMID 37407581, 2023). "There is scientific evidence that excessive protein consumption during early life leads to an increased insulin concentration, which promotes adipose tissue deposition and the risk of overweight, obesity, and type 2 diabetes in the subsequent years." (PMID 36839210, 2023). "In cohorts of people with adult-onset diabetes and clinically diagnosed type 2 diabetes, the presence of autoantibodies and elevated type 1 diabetes genetic risk is associated with progression to insulin treatment, highlighting a likely misdiagnosis." (PMID 37439792, 2023). "These cytokines are associated with type 2 diabetes by impairing insulin signal transduction and triggering IR." (PMID 36985331, 2023). "Independent genetic variants significantly associated with type 1 diabetes, type 2 diabetes, fasting insulin (FIns), fasting glucose (FGlu), 2 h-glucose post-challenge (2hGlu), and glycated hemoglobin (HbA1c) were selected as instrumental variables." (PMID 38066511, 2023). "Type 2 diabetes is a chronic disease caused by the insufficient secretion of insulin by the pancreas or the reduced action of the insulin produced." (PMID 36996235, 2023). "Human donor islets from carriers of type 2 diabetes risk alleles in RREB1 have altered glucose-stimulated insulin secretion ex vivo, consistent with a role for RREB1 in regulating islet cell function." (PMID 36633628, 2023). "Type 2 diabetes mellitus (T2DM) is a disease caused by insufficient or relatively insufficient insulin secretion, with elevated blood glucose as the main manifestation." (PMID 37113152, 2023). "Metabolic syndrome is associated with resistance to the effects of insulin on peripheral glucose and fatty acid utilization, leading to developing type 2 diabetes." (PMID 37095558, 2023). "The development of type 2 diabetes is mainly caused by two factors; impaired insulin secretion by pancreatic β-cells and the inability of insulin-sensitive tissues to respond to insulin." (PMID 37215099, 2023). "It was noted that in type 2 diabetes patients it was found that decreased levels of Akkermasia are associated with decreased insulin secretion." (PMID 36681683, 2023). "In this study, we used GWAS related to Fasting Glucose, Fasting Insulin, 2-h Glucose, HbA1c, and Type-2 Diabetes, GWAS data on Melanoma from risk on United Kingdom Biobank cohort study and FinnGen cohort study." (PMID 38179409, 2023). "Genetic variants in the insulin signalling pathway contribute to increased risk for type 2 diabetes." (PMID 36409629, 2023). "β‐cell dysfunction is an important phase for the onset and progression of type 2 diabetes hence, with a predicted loss of approximately 50% of insulin secretion." (PMID 37970433, 2023).
type 2 diabetes (continued). "Type 2 diabetes (T2D) is associated with compromised identity of insulin-producing pancreatic islet β cells, characterized by inappropriate production of other islet cell–enriched hormones." (PMID 37606041, 2023). "Certain polymorphisms in the CDKAL1 gene have been shown to be associated with a decrease in insulin sensitivity of the body’s tissues and an increased risk of type 2 diabetes." (PMID 37628646, 2023). "Our data demonstrate that female TgF344‐AD rats display a phenotype associated with type 2 diabetes, with elevated adiposity and impaired glucose tolerance/insulin sensitivity." (PMID 37095621, 2023). "Chronic low‐grade inflammation is a hallmark of type 2 diabetes, leading to impaired β cell islet structure and function, inducing hepatic IR, and impairing glucose tolerance by blocking glucose‐stimulated insulin secretion (GSIS)." (PMID 36601656, 2023). "Methylation patterns at certain CpG sites associated with intrauterine exposure have been linked to reduced insulin secretory function, higher body mass index, and a higher chance of developing type 2 diabetes later." (PMID 38292775, 2023). "Experiments in mice show that temporin G injection improves glucose tolerance and causes an increase in insulin secretion, suggesting its potential application in the treatment of type 2 diabetes." (PMID 36982501, 2023). "Type 2 diabetes (T2D) is a complex disorder associated with high blood glucose levels due to low insulin secretion or inadequate insulin action." (PMID 37698290, 2023). "The decreased insulin secretory capacity of β-cells observed in type 2 diabetes was associated with oxidative stress and inflammation in islet beta cells, causing beta cell death and loss of beta cell mass." (PMID 37280499, 2023). "HbA1c, C-peptide, insulin, and BMI, type 2 diabetes-associated parameters, were substantially high in male and female diabetic patients compared to the control subjects." (PMID 36869348, 2023). "A low BMI which reflects reduced pancreatic beta-cell secretory function is a common finding in adult African patients with type 2 diabetes and is often associated with the need for early initiation of insulin therapy." (PMID 37858088, 2023). "This variant promotes MAFA protein stability and predisposes subjects in their late 30’s to either adult-onset diabetes or insulinomatosis (i.e. non-syndromic insulin-producing β-cell tumors)." (PMID 37720527, 2023). "Previous studies have shown that the rs10946398 polymorphism of the CDKAL1 gene affects insulin secretion by pancreatic β-cells and is a risk factor for type 2 diabetes and gestational diabetes." (PMID 37628646, 2023). "Mistimed sleep, for example in shift workers, has been identified as a risk factor for developing type 2 diabetes, as this affects glucose tolerance and insulin sensitivity." (PMID 36930251, 2023). "In the UKPDS study, metformin in type 2 diabetes and overweight was shown to reduce the risk of ischaemic stroke compared to sulfonylureas or insulin." (PMID 37231200, 2023). "This pattern supports previous findings showing that the genus Flavonifractor decreased in prediabetes and increased in type 2 diabetes, and was associated with a lower insulin sensitivity and higher prevalence of dysglycemia." (PMID 36985331, 2023). "Oral antidiabetic treatment in COVID-19 patients was associated with a decreased mortality rate, but insulin therapy increased the risk of adverse outcomes in type 2 diabetes." (PMID 36983573, 2023). "A lower function AKT2 coding variant, p.Pro50Thr, occurs with high frequency (1.1%) in the Finnish population, and influences glucose uptake negotiated by insulin in target tissues, thus escalating the risk of type 2 diabetes in carriers." (PMID 37664840, 2023). "Several lifestyle interventions have been shown to mitigate the risk of prediabetes developing into type 2 diabetes by improving insulin sensitivity and consequently normalizing glucose regulation." (PMID 37258943, 2023).
type 2 diabetes (continued). "Of note, recent practice guidelines suggest the use of rtCGM for people with type 2 diabetes who take insulin and are at risk for hypoglycemia." (PMID 37676398, 2023). "Excessive iron accumulation has been found to be linked to diminished insulin secretion and the onset of type 2 diabetes, although the impact of metabolic disorders on serum ferritin levels remains a subject of debate." (PMID 38053120, 2023). "Losing weight can increase insulin sensitivity, reducing the risk of type 2 diabetes and can lower blood pressure." (PMID 36677012, 2023). "Research has demonstrated that lower-body muscle size is strongly associated with the development of type 2 diabetes, since insulin resistance is thought to originate in the lower-body muscles (e.g., leg muscles) and not in the arm muscles." (PMID 37797075, 2023). "Within the pancreatic islet, multiple cell types have been implicated in type 2 diabetes progression, most notably beta cells that secrete insulin in response to glucose stimulation, but also other cell types including alpha cells and delta cells." (PMID 37333221, 2023). "Investigate the effects of vitamin D3 supplementation on insulin sensitivity and β-cell function in adults at high risk for type 2 diabetes." (PMID 38068801, 2023). "The SNPs G972R, Gly972Arg, and rs1801278 of IRS-1 have shown a high prevalence in patients with type 2 diabetes and are caused by disrupted insulin signaling." (PMID 37664840, 2023). "Type 2 diabetes manifests when pancreatic β-cells fail to adapt to the increased insulin demand caused by insulin resistance." (PMID 38124083, 2023). "Specifically, methylation patterns at certain CpG sites associated with intrauterine exposure have been linked to reduced insulin secretory function, higher body mass index (BMI), and a higher chance of developing type 2 diabetes later." (PMID 38292775, 2023). "The fasting glucagon to insulin ratio is inversely associated with metabolic syndrome in patients with type 2 diabetes." (PMID 37762748, 2023). "Its overexpression has been associated with reduced insulin sensitivity, often leading to type 2 diabetes." (PMID 36671013, 2023). "Genes with upregulation after induced methylation of the Arx promoter were associated with a few pathways including the Type II diabetes mellitus and Insulin secretion." (PMID 37008919, 2023). "In clinical practice, insulin therapy is now widely used in the management of type 2 diabetes worldwide; however, it can cause iatrogenic hyperinsulinemia." (PMID 37324170, 2023). "Type 2 diabetes was characterized by insensitivity to insulin and a decrease in production, which ultimately caused pancreatic beta cell failure." (PMID 37903808, 2023). "We know that HCV interferes with the insulin-signaling pathway through multiple mechanisms, can infect the beta islet cells, is associated with circulating micro-RNAs, and has been linked to type II diabetes mellitus." (PMID 37851654, 2023). "Pancreatic β-cell dysfunction and insulin resistance underlie the onset of type 2 diabetes (T2D), while in type 1 diabetes (T1D), the immune system attacks pancreatic β-cells limiting insulin production." (PMID 36902254, 2023). "Unlike type 1 diabetes, which is caused by a deficiency of insulin, type 2 diabetes is often the result of insulin resistance, which means the body’s cells become less responsive to insulin’s signals to take up glucose from the bloodstream." (PMID 37446573, 2023). "Plant proteins, compared to animal proteins, have previously been shown to correlate with a reduced prevalence or risk of developing type 2 diabetes and lower fasting insulin and glucose in populations with type 2 diabetes." (PMID 37799765, 2023). "Our analysis revealed specific associations with body mass index, insulin secretion, and type 2 diabetes." (PMID 35036870, 2022).
type 2 diabetes (continued). "Clinical studies have shown renin angiotensin system blockade with valsartan prevents new-onset diabetes, and improves beta-cell function and insulin sensitivity in individuals at risk of developing type 2 diabetes." (PMID 35733766, 2022). "Meanwhile, it has been elucidated that a higher plasma concentration of IMP in type 2 diabetic patients, not only was negatively associated with microbial diversity, but also caused glucose intolerance by destroying insulin signaling." (PMID 36361652, 2022). "There was limited evidence of associations between sleep duration and fracture, type 2 diabetes, atrial fibrillation, fasting glucose, fasting insulin, or HbA1c." (PMID 36277903, 2022). "Type 2 diabetes mellitus (T2DM) is a metabolic disease caused by the loss of insulin sensitivity and pancreatic β-Cells failure." (PMID 36407109, 2022). "We used the ‘insulin secretion’ pPS of variants in eight genes associated with type 2 diabetes risk due to poor beta cell function: MTNR1B, HNF1A, GCK, TCF7L2, TMEM258, ADCY5, SLC3OA8 and ABO." (PMID 35247066, 2022). "Consumption of foods high in sugar and starches when the liver and pancreas cannot produce enough insulin to enter sugar into cells, causing a portion of the sugar to remain in the blood, represents type 2 diabetes." (PMID 36188660, 2022). "Glucagon‐like peptide‐1 (GLP‐1) receptor agonists are effective treatments for type 2 diabetes as they stimulate insulin release and promote weight loss through appetite suppression." (PMID 33880754, 2022). "Both type 1 and type 2 diabetes manifest with elevated circulating glucose levels caused by the deregulation of insulin signaling and/or the loss of functional insulin-producing β-cells." (PMID 35697798, 2022). "Genetic variants of glucagon-like peptide-1 receptor (GLP-1R) have been reported to affect insulin secretion and susceptibility to type 2 diabetes." (PMID 36528605, 2022). "The rs780094 SNP within GCKR gene was associated with liver fat accumulation, increased triglyceride concentrations, reduced insulin levels, and reduced risk of type 2 diabetes." (PMID 35333773, 2022). "Of note, in our data, the association between MR-proADM and incident type 2 diabetes was attenuated when we further controlled for insulin, hsCRP and leptin." (PMID 35681200, 2022). "It was also demonstrated in several studies that progression from normal glucose tolerance to type 2 diabetes was associated with worsening chiro-inositol deficiency due to the increasing resistance to insulin." (PMID 36156596, 2022). "Crucially, the insulin-dependent induction of cyclin D1 has been shown to be a risk factor for liver cancer in the context of obesity and/or type 2 diabetes." (PMID 36091143, 2022). "Our results based on the large randomly selected population-based METSIM cohort showed that increased leisure-time PA was associated with a lower incidence of type 2 diabetes and increased insulin sensitivity and insulin secretion." (PMID 35050191, 2022). "Type 2 diabetes is associated with a reduced beta cell mass and function, thus causing inadequate insulin production." (PMID 36232752, 2022). "Their upregulation and activation in β-cells under conditions of both type 1 and type 2 diabetes directly correlates with β-cell failure; β-cell death and loss of insulin secretory function through disturbance of cell survival control mechanisms." (PMID 35136063, 2022). "Glucotoxicity plays a pathogenic role in the early stages of type 2 diabetes mellitus (T2DM) as in vivo evidence reveals the loss of first-phase insulin secretion along with elevating plasma glucose." (PMID 35057503, 2022). "Further, IBS patients had increased risk of type 2 diabetes and elevated levels of C-peptide and insulin compared to controls." (PMID 35565656, 2022). "Fasting lactate levels have been reported to be increased in obese and type 2 diabetics compared to healthy individuals, and associated with insulin resistance." (PMID 36111162, 2022).
type 2 diabetes (continued). "HNF4A crucially performs hepatic gluconeogenesis regulation and insulin secretion, and the corresponding gene was shown to be linked to type 2 diabetes (T2DM) in several studies." (PMID 36360783, 2022). "Adolescent cohort studies have demonstrated significant associations between TRAP exposure and the risk factors for Diabetes Mellitus Type II, such as lower insulin sensitivity and higher abdominal adiposity, fasting insulin, and fasting glucose." (PMID 34417545, 2022). "Along with these factors, type II diabetes is associated with increased brain oxidative stress, increased hippocampal AGEs, and impaired brain insulin signaling." (PMID 35781592, 2022). "Whereas, Type-2 diabetes accounts for 90% of cases and is caused by resistance of tissues to insulin action and decrease insulin secretion." (PMID 35086537, 2022). "Insulin resistance, a hallmark of Type-2 diabetes, is defined by a reduced ability of insulin to promote glucose uptake into fat and muscle." (PMID 35313696, 2022). "The use of sacubitril/valsartan has been associated with improved glycemic control and insulin sensitivity in individuals with type 2 diabetes and/or obesity." (PMID 35733766, 2022). "In relation to type 2 diabetes, statistically significant interactions with fasting glucose, insulin rAUC0−120, and triglyceride were observed, and for all outcomes, the associations were more driven by the group of individuals with known type 2 diabetes." (PMID 35575196, 2022). "There are limited data on behavior changes associated with glycemic improvement in patients with type 2 diabetes on less intensive insulin regimens." (PMID 34962151, 2022). "Genome Wide Association Studies (GWAS) have identified genetic loci associated with β-cell function and glucose-stimulated insulin release as Type 2 Diabetes susceptibility alleles." (PMID 36672613, 2022). "•Individuals with type 2 diabetes in lower socioeconomic positions had a higher risk of insulin initiation." (PMID 36033350, 2022). "It has been confirmed that insulin malfunction precedes hyperglycemia development among people at increased risk of developing type 2 diabetes, and patients with type 2 diabetes have suffered from IR over the years." (PMID 35742405, 2022). "Visceral adiposity and glucose intolerance subsequent to overfeeding, as well as to altered insulin signaling and progressive loss of beta-cell function, represent well established features of MetS and type 2 diabetes (T2DM)." (PMID 35631195, 2022). "Studies from the diaspora suggest that insulin clearance is the primary defect underlying the development of type 2 diabetes." (PMID 36166072, 2022). "Resolving these glucose toxicities is pivotal in type 2 diabetes therapy because the decline in insulin secretion and insulin sensitivity causes further hyperglycemia." (PMID 35844351, 2022). "Our previous data showed that Iraqi immigrants have a higher risk of developing type 2 diabetes at an earlier age compared to native Swedes, which suggests that β-cell dysfunction and impaired insulin sensitivity appear at younger ages." (PMID 36247141, 2022). "Type 2 diabetes mellitus (T2D) is a chronic metabolic disorder associated with impaired insulin metabolism and hyperglycemia." (PMID 36595825, 2022). "Glucose levels, glucose intolerance, insulin levels, triglyceride (TG), and total cholesterol (TC) levels were examined on week 12, which recapitulated the hallmark features of type II diabetes." (PMID 36312255, 2022). "Oleic and linoleic acids have also been linked to the lower risks of type 2 diabetes, inhibiting negative regulators in the insulin pathway and linking linoleic acid to stimulating insulin secretion." (PMID 35811969, 2022). "MiR-223-3p has been demonstrated to act as a potential biomarker and molecule for pre-onset dysfunction in type 2 diabetes, of which low levels of miR-223-3p are associated with impaired insulin sensitivity." (PMID 36212957, 2022).